IL6 (interleukin 6)
Diseases named in the same sentence as IL6 in open-access papers (continued):
Sharing a sentence is not in itself a finding about the gene and the disease.
coronary artery disease (continued). "Cardiovascular diseases, including atherosclerotic heart disease, coronary heart disease (CHD), congestive heart-failure (CHF), and other cardiovascular diseases, have been associated with elevated levels of IL-1β, IL-6, TNF-α, and IFN-γ." (PMID 24995360, 2014). "Unfortunately, there are contradictory data regarding the role of IL-6 in the development of coronary heart disease in women." (PMID 25000444, 2014). "Interleukin-6 (IL-6) is a well-known inflammatory cytokine and suggested to be involved in the development of coronary artery disease (CAD)." (PMID 24363620, 2013). "Baseline concentrations of proinflammatory cytokine IL-6 was significantly higher in patients with coronary artery disease." (PMID 23984427, 2013). "IL-1Ra and IL-6 are significantly increased in coronary artery disease (CAD) patients compared with healthy individuals." (PMID 23028694, 2012). "In patients with coronary artery disease, dobutamine-induced ischemia resulted in an increase in plasma levels of IL-6 and tissue factor." (PMID 23091596, 2012). "In clinical studies, the levels of high sensitivity C-reactive protein (hs-CRP) and interleukin-6 (IL-6) are commonly used as inflammatory markers that contribute the early stages of coronary artery disease." (PMID 23029185, 2012). "Although IL-6 has traditionally been reported to play an important role in the pathogenesis of coronary artery disease and atherosclesoris, the possibility that IL-6 has many beneficial effects on health has been put forward recently." (PMID 21599899, 2011). "Several studies have established that CRP serum levels and other inflammatory markers (cytokines such as IL-1, IL-6, and TNF-α) are risk factors for coronary disease, although their levels are elevated in both coronary disease and chronic infections." (PMID 28348657, 2011). "It plays an important role in the pathogenesis of coronary artery disease and large quantities of IL-6 are found in human atherosclerotic plaques." (PMID 20937099, 2010). "This study was designed to explore the possible association between LVDD and proinflammation reflected by IL-6 and TNF-α levels in subjects with stable coronary artery disease." (PMID 19909503, 2009). "During destabilization of coronary heart disease, cytokines released by inflammatory cells mediate further inflammatory cell migration and cardiac repair and, particularly IL-6, mediates CRP elevation." (PMID 19503842, 2009). "Further, endothelial and vascular smooth muscle cells may express IL-6 receptors dependent on IL-1 activity, indicating the relevance of IL-6 in atherosclerotic and subsequent ischemic heart disease." (PMID 39969632, 2025). "Moreover, circulating levels of IL-6 and CRP have been linked to elevated endothelial microparticles in coronary heart disease." (PMID 41155389, 2025). "RA patients had significantly higher levels of IL-1β, IL-6, and IL-18 compared to controls.Disease activity (DAS-28) and RF positivity were major risk factors for ischemic heart disease in RA.Better disease control and remission can reduce cardiac complications in RA patients." (PMID 41179568, 2025). "Similarly, the role of IL-6 in cardiovascular disease is being actively investigated in ongoing clinical trials evaluating anti–IL-6 therapies in patients with coronary artery disease and chronic kidney disease." (PMID 40141381, 2025). "This is similar to MR findings for coronary heart disease, where IL-6 but not CRP have been shown to play a potential causal role." (PMID 38699368, 2024). "Therefore, the current study aims to delve into the potential applications and prognostic significance of Gal-3, FKN, IL-6, miR-21, and cTnI in ischemic heart disease patients, with the goal of advancing clinical management strategies." (PMID 38935941, 2024).
coronary artery disease (continued). "In particular, the ingestion of olive oil phenolic compounds has been associated with a decrease in levels of interleukin-6 (IL-6) and C-reactive protein (CRP) in patients with stable coronary heart disease and it is proposed as a supplementary intervention to the pharmacological agenda." (PMID 39125686, 2024). "Keyword analysis results identified “mendelian randomization,” “inflammation,” “interleukin-6,” “c-reactive protein,” “coronary-heart-disease” as the top 5 most frequently used keywords that reflect current hotspots and prospective future trends in this field of research." (PMID 38579070, 2024). "In addition to analyzing IL-6, two of the previous studies also analyzed D-dimer, a protein that can be indicative of blood clotting and is predictive of coronary heart disease." (PMID 38300637, 2024). "Although in patients with coronary artery disease, IL-6 levels were associated with AFIB, but not TNFα, IL-6 levels were higher in AFIB patients than non-AFIB controls." (PMID 38256155, 2024). "Moreover, PCSK9 inhibitors suppress the accumulation of the proinflammatory cytokine IL-6 in the plasma of stable coronary artery disease patients with the IL6-74CC genotype and high level of lipoprotein(a)." (PMID 36970356, 2023). "Overall, in humans, the net actions of IL-6 promote ischemic heart disease and its complications." (PMID 37259918, 2023). "Others revealed that serum MCP-1 levels were associated with coronary artery disease, as measured by the coronary artery calcium score, and increased plasma levels of IL-6 and TNF-alpha were associated with left ventricular diastolic dysfunction in patients with stable coronary artery disease." (PMID 37892788, 2023). "However, the main focus was single exposures or common exposure factors, such as interleukin-6 (IL-6), seven sleep characteristics, serum uric acid levels, iron status, and coronary artery disease." (PMID 37056283, 2023). "Studies measuring IL-6 levels in blood samples of coronary heart disease patients have found elevated IL-6 levels in the coronary heart disease group compared with healthy individuals, with more severe disease correlating with higher levels of this inflammatory marker." (PMID 37958528, 2023). "Our results are in accordance with previous studies reporting the anti-inflammatory actions of pioglitazone in coronary arteriosclerosis by reducing the expression of CCL2 receptor (CCR2) as well as in traumatic brain injury by modulating the PPARγ/NF-κB/IL-6 pathway." (PMID 37958504, 2023). "The cytokine IL-6 has well-known proinflammatory roles in aging and ischemic heart disease." (PMID 37259918, 2023). "In conclusion, this study confirmed the relationship between circulating endothelial progenitor cells and the severity of coronary artery disease in unstable angina pectoris, which may be related to the IL-6 level." (PMID 35847417, 2022). "In the present study, because we selected patients excluding the most common inflammatory confounders that could raise IL-6, we were able to include patients with even normal levels of IL-6, despite the established coronary disease." (PMID 36028849, 2022). "IL-6 is also predictive of cardiovascular events in patients with stable coronary disease." (PMID 36028849, 2022). "The genotypic summary of the IL-6 gene revealed that there is no contribution in the assorted class of inflammatory-associated diseases like coronary artery disease, coronary heart disease, and Alzheimer's disease." (PMID 35673309, 2022). "We aimed to elicit the pro-inflammatory effect of galectin-3 as determined by interleukin-6 (IL-6) serum levels and to explore the relationship between galectin-3 (LGALS-3 rs4652) gene variant and its expression levels with coronary artery disease (CAD) risk among T2DM Egyptian patients." (PMID 34616230, 2021).
coronary artery disease (continued). "Analyzing these marker levels according to the number of coronary lesions, we obtained an increased IL6 value that was similar for patients with microvascular angina, one-vessel, and two-vessel coronary disease, but significantly lower than in women with three-vessel coronary lesions." (PMID 34683106, 2021). "In this context, the current study aims to analyze whether certain inflammatory markers, i.e., interleukin 6 (IL-6) and endothelin 1 (ET-1), can play a role in the diagnosis of ischemic heart disease through microvascular involvement in women." (PMID 34683106, 2021). "This may explain the higher value of IL-6 in the group of patients with obstructive coronary heart disease." (PMID 34683106, 2021). "Links between higher IL-6 levels and an elevated risk of cardiovascular events among otherwise healthy individuals are well documented, and IL-6 has also been proposed to be a predictor of coronary artery disease (CAD) severity and associated mortality among ACS patients." (PMID 34861824, 2021). "Plasma IL-6 levels are significantly elevated in patients with coronary heart disease and are not affected by other risk factors." (PMID 34231707, 2021). "In addition, in patients with unstable coronary artery disease, circulating IL-6 was a strong independent marker of increased mortality." (PMID 32485823, 2020). "In a cohort of 981 patients with coronary heart disease enrolled in the Heart and Soul study, HCV seropositivity was associated with changes in levels of CRP, TNF‐α, IL‐6 increased Framingham risk scores, and hospitalizations due to clinical cardiac failure and death." (PMID 31785111, 2020). "This association is further underscored by recent reports describing that glucose over-utilization drives the excessive production of IL-6 and IL-1β by monocytes and macrophages derived from patients with coronary artery disease, by a process that is dependent on redox-sensitive STAT3 signaling." (PMID 32350546, 2020). "IL-1β is known to drive the IL-6 signaling pathway, and therefore, this pathway could be another potential therapeutic target in the treatment of coronary artery disease." (PMID 30367209, 2019). "Furthermore, regular physical exercise is thought to reduce IL-6 level and ischemic events in men with stable coronary artery disease." (PMID 31739518, 2019). "We chose to focus on IL6, based on its known importance in human coronary artery disease." (PMID 31658298, 2019). "For example, a-linolenic acid (18:3(n-3)), extracted from a specific nut was inversely associated with CRP, IL-6, soluble tumor necrosis factor (TNF) receptors 1 and 2 and fibrinogen levels in healthy individuals and/or patients with stable coronary artery disease." (PMID 30131846, 2018). "High levels of IL-6 have also been proved to be associated with cardiovascular diseases and the development of coronary disease in people without clinically established cardiac vascular diseases." (PMID 27412561, 2016). "In the general population, IL-6 may predict mortality in patients with unstable coronary artery disease, and identify candidates that benefit from an early invasive treatment." (PMID 26544186, 2015). "Epicardial adipose tissue expresses and secretes several bioactive molecules including interleukin (IL)-1, IL-1β, IL-6, IL-8, and IL-10, the levels of these interleukins were found as significantly higher in subjects with coronary artery disease when compared to healthy subjects." (PMID 25887962, 2015). "It has been reported that elevated levels of inflammation biomarkers, especially that of C-reactive protein (CRP) and interleukin-6 (IL-6), are inversely associated with various HRV indices in apparently normal adults and in patients with coronary heart disease (CHD)." (PMID 24722336, 2014). "Circulating levels of IL-6 represent a strong independent marker of increased mortality among patients with unstable coronary artery disease, and may be useful in directing subsequent care." (PMID 24733347, 2014).
coronary artery disease (continued). "IL-6 is a cytokine that has been proven to be crucially involved in ischemic heart disease." (PMID 23509814, 2013). "Our findings are consistent with and extend those of previous studies showing the potential of inflammatory pathways as targets for cardiovascular disease prevention and highlight the need for studies of IL-6 signalling inhibition for the prevention of coronary artery disease." (PMID 23818744, 2013). "It has been shown that EAT produces inflammatory mediators such as interleukin (IL)-6, IL-1b, tumor necrosis factor (TNF)-a, and monocyte chemotactic protein (MCP-1) in patients with significant coronary artery disease and expresses mRNAs of adiponectin, resistin, leptin, IL-6, TNF-a, and CD-45." (PMID 23762053, 2013). "For example, a reduction in pro-inflammatory levels (TNF-a and IL-6) was found in patients with coronary heart disease following aerobic exercise training, and lower IL-6 concentrations have been observed in individuals who had self-reported higher physical activity levels." (PMID 24223557, 2013). "Furthermore, after 12 weeks of aerobic exercise, IL-6 level was found to be decreased while IL-10 level was increased in type 2 diabetic patients and the patients with coronary heart disease." (PMID 24392457, 2013). "Also, it has been shown that levels of C-reactive protein (CRP), IL-6, and TNF-α were higher in patients with coronary artery disease (CAD) and were linked to an increased risk of adverse cardiac events and mortality." (PMID 22830072, 2012). "IL-6 is higher in the sera of patients with T1D, T2D and in patients with coronary artery disease." (PMID 16939660, 2006). "Determination of the combination of GDF-15, IL-6, LCN-2, and TIM-3 markers can indeed complement coronary angiography in the diagnosis, risk assessment, and management of coronary artery disease (CAD)." (PMID 39330316, 2024). "A previous MR analysis suggested that reduced IL-6 signalling (modelled using rs2228145 alone) could reduce inflammation and risk of coronary heart disease, leading to clinical trials of monoclonal antibodies targeting either IL6R or IL-6 for coronary disease prevention." (PMID 36716318, 2023). "A previous study based on the analysis of two population-based cohorts suggested that circulating serum IL-6 levels could be associated with increased coronary risk (defined as nonfatal MI or fatal coronary heart disease [CHD])." (PMID 36028849, 2022). "Previous studies could not demonstrate the association between IL-6 gene polymorphisms (which had been associated with coronary artery disease) and carotid atherosclerosis." (PMID 36060677, 2022). "It has been shown that α-linolenic acid [18:3(n-3)], extracted from nut is inversely associated with interleukin-6 (IL-6), soluble tumor necrosis factor (TNF) receptors 1 and 2, fibrinogen, and C-reactive protein (CRP) levels in both healthy subjects and individuals with coronary artery disease." (PMID 35425791, 2022). "The accumulation of cardiac fat is also associated with higher levels of pro-inflammatory cytokines such as IL-6, IL-1, TNF-α, and the expression of adipokine fatty acid-binding protein 4 (FABP4) that are associated with the development of MetS and the extent of coronary artery disease." (PMID 33752666, 2021). "In addition to elevation of the proinflammatory cytokines IL1β, TNF-α and IL-6, exercise may reduce C-reactive proteins in patients with coronary arteriosclerosis and Type II T helper cytokines (IL-5 and IL-13) in asthmatic BALB/c mice." (PMID 32778140, 2020). "Nevertheless, data available from the PRIME study (multicenter prospective cohort designed to identify risk factors for coronary heart disease) could not reveal an association with SCD when assessed with other biomarkers such as IL-6 or CRP." (PMID 32093244, 2020).
coronary artery disease (continued). "The concentration of interleukin 6 (IL-6), as a proinflammatory cytokine, increases in bronchoalveolar lavage fluid (BALF), and in the lung upon exposure to particulate matter, but its high concentration in the blood poses a cardiovascular risk factor in patients with coronary artery disease." (PMID 31579452, 2019). "Acute exercise induces a transient inflammatory response through the increase in several cytokines such as interleukin-6, tumor necrosis factor-α, C-reactive protein, and nuclear factor kappa B and oxidative stress in healthy subjects and in subjects with coronary artery disease." (PMID 26557715, 2015). "The predictive value of these markers, including interleukin-6 (IL-6), has been demonstrated for subjects with existing coronary artery disease (CAD) and apparently healthy subjects." (PMID 23818744, 2013). "There were significant differences before or after subgroup analyses in the stratum of coronary artery disease [SMD = −0.70, 95% CI (−1.82, 0.42), p > 0.05] and the stratum of ischaemic stroke [SMD = −0.43, 95% CI (−2.91, 2.05), p > 0.05] for IL-6." (PMID 40017522, 2025). "We observed three major differences between the two groups of patients: the level of IL-6 and NEUT-GI at ICU admission and the presence of coronary artery disease in patients’ history." (PMID 40142279, 2025). "It has been demonstrated that patients with coronary artery disease show lower SIRT1 mRNA expression and higher IL-6 expression in blood monocytes versus healthy controls." (PMID 41228388, 2025). "In addition, another study shows that the hypomethylation of IL‐6 and tumor necrosis factor‐alpha (TNF‐α) genes in obese patients can lead to endothelial dysfunction by causing inflammation and oxidative stress, thus promoting the occurrence of atherosclerosis and coronary artery disease." (PMID 38405061, 2024). "This cross-sectional study investigated the association between dietary fatty acid intake and inflammatory markers, such as IL-6, and high sensitivity C-reactive protein (hs-CRP) in patients with coronary artery disease (CAD)." (PMID 38605945, 2024). "Studies by other authors also found elevated serum IL-6 levels in SLE patients with heart failure, coronary artery disease, and ischemic heart disease." (PMID 37371554, 2023). "Studies have found that the expression level of has-miR-296-a was positively correlated with the serum levels of IL-6 and TNF-α, which were increased in patients with coronary heart disease." (PMID 37491214, 2023). "The development of coronary artery disease (CAD) is related to the impaired quantity and composition of inflammatory proteins found in plasma and tissue, such as interleukin 6 (IL-6), adipokines, and resistin." (PMID 36624488, 2023). "Lutein is swallowed by blood mononuclear cells and it is capable to inhibit both gene expression and secretion of IL-6, IL-1β, and tumor necrosis factor (TNF) in stable coronary artery disease patients." (PMID 37655002, 2023). "Therefore, it is of interest to examine IL-6's ability to predict the existence ofearly coronary artery disease (CAD)." (PMID 38250529, 2023). "Previous studies have found increased secretion of leptin and IL-6 and decreased secretion of cardioprotective lipocalin in EAT in patients with coronary artery disease, leading to immune cell activation and inflammatory responses." (PMID 36158806, 2022). "The SNP rs2228145 A/C in IL-6 R gene has been associated with lower circulating inflammation biomarkers in coronary artery disease (CAD), such as C-reactive protein (CRP), IL-6, and fibrinogen." (PMID 36428884, 2022). "Clinical experiments have found significantly reduced levels of plasma interleukin-6 (IL-6), interferon-α (IFN-α), and C-reactive protein (CRP) after taking the PPARα agonist (fibrate) in patients with coronary heart disease confirmed by angiography." (PMID 33728018, 2021).